MT-ATP6 (mitochondrially encoded ATP synthase membrane subunit 6)
Description:
Subunit a, of the mitochondrial membrane ATP synthase complex (F(1)F(0) ATP synthase or Complex V) that produces ATP from ADP in the presence of a proton gradient across the membrane which is generated by electron transport complexes of the respiratory chain (Probable). ATP synthase complex consist of a soluble F(1) head domain - the catalytic core - and a membrane F(1) domain - the membrane proton channel. These two domains are linked by a central stalk rotating inside the F(1) region and a stationary peripheral stalk. During catalysis, ATP synthesis in the catalytic domain of F(1) is coupled via a rotary mechanism of the central stalk subunits to proton translocation (Probable). With the subunit c (ATP5MC1), forms the proton-conducting channel in the F(0) domain, that contains two crucial half-channels (inlet and outlet) that facilitate proton movement from the mitochondrial intermembrane space (IMS) into the matrix. Protons are taken up via the inlet half-channel and released through the outlet half-channel, following a Grotthuss mechanism.
Synonyms: ATP6; ATPase-6; Su6m; formerly MTATP6; RP
Tractability: Small molecule: a structure with a bound ligand is known. Antibody: UniProt predicts a signal peptide or a membrane-spanning region.
Gene: Protein-coding gene on chromosome MT (8,527 to 9,207, forward strand). Ensembl gene ENSG00000198899.
Subcellular location: Mitochondrion inner membrane
Pathways (Reactome):
Metabolism of proteins: Mitochondrial protein degradation; Mitochondrial translation termination
Metabolism: Formation of ATP by chemiosmotic coupling
Organelle biogenesis and maintenance: Cristae formation
Gene Ontology:
Molecular function: protein binding; proton channel activity; proton-transporting ATP synthase activity, rotational mechanism; proton transmembrane transporter activity
Biological process: proton motive force-driven ATP synthesis; proton motive force-driven mitochondrial ATP synthesis; proton transmembrane transport; response to hyperoxia
Cellular component: mitochondrion; proton-transporting ATP synthase complex; mitochondrial inner membrane
Gene-disease validity (ClinGen):
ClinGen rates the evidence that MT-ATP6 causes each of these diseases.
Leigh syndrome (mitochondrial): Definitive. A progressive neurological disease defined by specific neuropathological features associating brainstem and basal ganglia lesions.
mitochondrial disease (mitochondrial): Definitive.
Homologues: Orthologues: chimpanzee MT-ATP6 (94% identical), pig ATP6 (79% identical), guinea pig MT-ATP6 (78% identical), rabbit ATP6 (77% identical), macaque ATP6 (76% identical), mouse mt-Atp6 (76% identical), rat Mt-atp6 (75% identical), tropical clawed frog ATP6 (53% identical), zebrafish mt-atp6 (52% identical), Drosophila melanogaster mt:ATPase6 (37% identical).
Diseases named in the same sentence as MT-ATP6 in open-access papers:
MT-ATP6 is named in the same sentence as 150 diseases in open-access papers, as found by Europe PMC text mining. Sharing a sentence is not in itself a finding about the gene and the disease. The quoted sentences say what the papers report.
Leigh syndrome (45 papers, 2010 to 2025). "The MT-ATP6 gene, encoding a subunit of mitochondrial complex V, represents one of the most frequently mutated genes in Leigh syndrome." (PMID 41300639, 2025). "This case highlights important distinctions from previously reported MT-ATP6-associated Leigh syndrome cases." (PMID 41300639, 2025). "Mitochondrial pathogenic variants frequently implicated in Leigh disease include those in the MT-ATP6 gene, which affects the complex V of the electron transport chain and results in a loss of ATP-synthetic activity." (PMID 40149498, 2025). "MILS, which is a subset of Leigh syndrome, is a second common disorder associated with pathogenic MT-ATP6 variants whose first variant was reported in 1992." (PMID 38396915, 2024). "Classic syndromic phenotypes associated with MT-ATP6 mutations are Leigh syndrome (OMIM #256,000), NARP (neuropathy, ataxia and retinitis pigmentosa; OMIM #551,500) and hypertrophic cardiomyopathy." (PMID 38755691, 2024). "The m.8993T>G; p.(Leu156Arg) variant in the MT‐ATP6 gene is a commonly reported pathogenic variant which can cause Leigh syndrome (as seen in this patient) or Neuropathy Ataxia Retinitis Pigmentosa." (PMID 39095335, 2024). "Pathogenic variants in the MT‐ATP6 gene (m.8993 T > G, p.Leu156Arg, m.8993T>C, p.Leu156Pro and m.9176T>C, p.Leu217Pro) were the most common (n = 9) mtDNA etiologies in our Leigh syndrome cohort." (PMID 34716721, 2022). "Pathogenic mutations in MT-ATP6 are typically linked to Leigh syndrome (subacute necrotizing encephalomyelopathy) or the syndrome of neuropathy, ataxia and retinitis pigmentosa (NARP)." (PMID 34635923, 2022). "Mutations in mitochondrial DNA encoded subunit of ATP synthase, MT-ATP6, are frequent causes of neurological mitochondrial diseases with a range of phenotypes from Leigh syndrome and NARP to ataxias and neuropathies." (PMID 34635923, 2022). "Mutation m.8993T>G in the MT-ATP6 gene (F-ATPase protein 6) specific for Leigh disease was detected in proband 3; this mutation was almost homoplasmic (close to 100%)." (PMID 34829316, 2021). "Couple 1 was referred for PGD because their son had Leigh syndrome due to the m.8993T>G mutation in the MTATP6 gene, with 90% mutant load in skeletal muscle." (PMID 27450679, 2017). "Couple 4 was referred to discuss their reproductive options because their son had Leigh syndrome caused by an almost homoplasmic m.8993T>G mutation in the MTATP6 gene, demonstrated in his blood, fibroblasts and skeletal muscle." (PMID 27450679, 2017). "Abnormal neurological findings were reported in three mothers to children with Leigh syndrome, who carried the same mutations as their children -two with PDHc deficiency and one with a pathogenic mutation in MT-ATP6." (PMID 24731534, 2014). "The mitochondriopathy resulting from the mutation in gene MTATP6 has an extremely variable clinical phenotype including Leigh syndrome (LS), neurogenic muscle weakness, ataxia, retinitis pigmentosa (NARP), and occasionally asymptomatic patients." (PMID 25548692, 2014). "Variants in MT-ATP6 have been shown to cause a number of symptoms such as ataxia, cognitive dysfunction, neuropathy, seizures, and retinopathy; however, it is most commonly known to cause mitochondrial complex V deficiency, Leigh syndrome, and/or neuropathy, ataxia and retinitis pigmentosa (NARP)." (PMID 35699875, 2022). "The majority of mitochondrial ATP6 synthase disorders result from missense mutation in MT-ATP6; moderate mutant levels (70%–90%) present with early onset ataxia, learning difficulties, and retinal involvement while patients with higher mutant loads (>90%) develop maternally inherited Leigh syndrome." (PMID 32042910, 2020). "Leigh syndrome (LS), subacute necrotizing encephalomyelopathy is caused by various genetic defects, including m.9185T>C MTATP6 variant." (PMID 29116603, 2018).
Leigh syndrome (continued). "Expanded exome sequencing using a hybrid nuclear exome and mitochondrial DNA panel identified a pathogenic variant in the MT-ATP6 gene (m.8993T>G), confirming the diagnosis of MT-ATP6-related mitochondrial disease manifesting as Leigh syndrome (OMIM:551500)." (PMID 41300639, 2025). "An infant referred for suspected congenital torticollis was ultimately diagnosed with MT-ATP6-related Leigh syndrome." (PMID 41300639, 2025). "We present an instructive case of an infant initially evaluated for suspected congenital torticollis who ultimately received a diagnosis of MT-ATP6-related Leigh syndrome." (PMID 41300639, 2025). "MT-ATP6 pathogenic variants have been linked to a broad variety of phenotypes besides the most known NARP and Leigh syndromes, including cases of spinocerebellar ataxia (SCA)." (PMID 38755691, 2024). "For example, MT-ATP6-related Leigh disease has been reported in cases with adult onset or in patients with MRI findings that differ from classic MILS, presenting delayed myelination, cerebral atrophy/microcephaly, or no pathology." (PMID 38396915, 2024). "MT‐ATP6 deficiency caused by m.8993T>G mutation and MT‐ND5 deficiency induced a severe form of Leigh syndrome." (PMID 31967322, 2020). "MT-ATP6 is one of the important genes which encodes ATP synthase F0 subunit 6; fluctuation of this genes activity is associated with diseases such as LHON, Leigh syndrome, neuropathy, ataxia, and retinitis pigmentosa, NARP, and bilateral necrosis of striation." (PMID 25695052, 2015). "MT-ATP6 mutations have been previously found in patients with primary open-angle glaucoma (POAG), primary angle-closed glaucoma, neuropathy, ataxia, retinitis pigmentosa, and mitochondrial DNA-associated Leigh syndrome." (PMID 36004037, 2022). "Comparison with data we achieved for the m.8993T > G mutation (MT-ATP6 gene), responsible for the NARP/Leigh syndrome, indicates that these mutations differentially influence mtDNA segregation during oogenesis, while their impact is similar in developing somatic tissues." (PMID 21120938, 2011). "Unlike Leigh syndrome, MILS is exclusively maternally inherited due to its basis in mtDNA pathogenic variants, and 100% of cases are due to mtDNA pathogenic variants, specifically in the MT-ATP6 gene." (PMID 40149498, 2025).
Ataxia (37 papers, 2010 to 2026). Ataxia refers to impaired coordination of voluntary muscle movement. "The m.8993T>G transversion in the Homo sapiens MT-ATP6 gene disrupts the proton channel of ATP synthase, causing neuropathy, ataxia, and retinal degeneration at high mutant loads." (PMID 41300750, 2025). "NARP syndrome, characterized by neuropathy, ataxia, and retinitis pigmentosa, is primarily linked to pathogenic variants in mtDNA, particularly in the MT-ATP6 gene." (PMID 40149498, 2025). "The m.8993T>G mutation in the Homo sapiens MT-ATP6 gene leads to neurogenic muscle weakness, ataxia, and retinitis pigmentosa (NARP) when heteroplasmy exceeds approximately 70%." (PMID 41300750, 2025). "Although classically associated with the NARP syndrome, recent evidence highlights an important role of MT-ATP6 pathogenic variants in complicated adult-onset ataxias." (PMID 38755691, 2024). "The m.9035T>C p.(Leu220Pro) variant in the MT‐ATP6 gene has been reported in multiple families with spinocerebellar ataxia." (PMID 39095335, 2024). "We studied here an unusual heteroplasmic truncating mutation in MT-ATP6, identified in a patient with adult-onset axonal neuropathy, ataxia and IgA nephropathy." (PMID 34635923, 2022). "Here we investigated the functional consequences of an unusual heteroplasmic truncating mutation m.9154C>T in MT-ATP6, which caused peripheral neuropathy, ataxia and IgA nephropathy." (PMID 34635923, 2022). "Descriptions of peripheral neuropathy or spinocerebellar ataxia (SCA) with upper motor neuron (MN) signs have extended the MT-ATP6 associated diseases to nonsyndromic phenotypes." (PMID 34635923, 2022). "The high prevalence of pathogenic MT-ATP6 variants suggests that analysis of this gene should be included in the routine workup of both hereditary and sporadic ataxias." (PMID 34037856, 2021). "The m.8993T > C mutation in the mtDNA ATP synthase subunit 6 gene (MTATP6) has been described in two main mitochondrial disorders, namely Leigh syndrome and neuropathy, ataxia and retinitis pigmentosa (NARP)." (PMID 32443735, 2020). "Craig and colleagues in 2007 screened for the m.8993T > C MTATP6 mutation a large sample of patients with unexplained ataxia (total number 308) or Charcot-Marie-Tooth (n." (PMID 32443735, 2020). "It is found that mutations in the MT-ATP6 gene result in neuropathy, ataxia, and retinitis pigmentosa, which lead to muscle weakness, vision loss, and the other features." (PMID 25695052, 2015). "Based on this study and our clinical experience, mtDNA analysis is especially useful in undiagnosed patients with peripheral neuropathy, spasticity or ataxia, in whom MT‐ATP6 pathogenic variants may have been missed." (PMID 39095335, 2024). "Indeed, recent cohort studies have concluded that MT-ATP6 mutations cause a spectrum of mitochondrial diseases, in which neuropathy and/or ataxia are frequently observed." (PMID 34635923, 2022). "Neuropathy, ataxia and retinitis pigmentosa syndrome (NARP), also associated with the8993T>G mutation in the MT-ATP6 mitochondrial gene, usually occurs in youngadults, as a combination of salt-and-pepper retinopathy, muscle weakness, ataxia,and sensory neuropathy." (PMID 30379275, 2018). "Thus, in the two patients with a homoplasmic mutation in the mtDNA gene MT-ATP6 (P14 and P15), the highest sNFL levels were detected in P15, with ataxia, dysarthria, epilepsy, optic atrophy, cognitive impairment and polyneuropathy as compared to P14 with polyneuropathy." (PMID 34975387, 2021). "The presence of the ATP6 mutation typically suggests Leigh or NARP (Neuropathy, Ataxia, and Retinitis Pigmentosa) syndrome, which occurs in over 50% of patients with MT-ATP6 mutations." (PMID 40002882, 2025). "The m.8951T>C/MT-ATP6 was detected in a patient with ataxia, while the m.8412T>C/MT-ATP6 was shown in a patient with LHON in combination with a known pathogenic mutation and proposed as possible helper change in the disease onset." (PMID 39866453, 2025).
Ataxia (continued). "Mutations in MT-ATP6 have been associated with clinical pictures ranging from isolated ataxia to NARP (Neuropathy, Ataxia, and Retinitis pigmentosa), bilateral striatal necrosis, and Leigh syndrome." (PMID 38790246, 2024). "Neuropathy, ataxia, and retinitis pigmentosa (NARP) are caused by a mutation in the gene encoding subunit 6 of mitochondrial H(+)-ATPase (MTATP6)." (PMID 36295857, 2022). "We expand the clinical and molecular spectrum of MT-ATP6-related mitochondrial disorders to include leukodystrophy, renal disease, and myoclonic epilepsy with cerebellar ataxia." (PMID 32042910, 2020). "Our findings highlight the importance of including MT‐ATP6 gene sequencing in the gene panels of spinocerebellar ataxia and hereditary neuropathy." (PMID 31187502, 2019). "The phenotype of ataxias caused by MT-ATP6 mutations is clinically not different from late-onset autosomal forms of ataxia." (PMID 34401960, 2021). "Interestingly, the 2 patients with the lowest regional BPND in cerebellar gray matter both presented with ataxia (patient 1 with an SPG7 mutation and patient 8 with an MT-ATP6 mutation)." (PMID 33883237, 2021). "The phenotype of ataxia caused by mutations in MT-ATP6 can frequently not be distinguished from ataxias caused by nuclear gene mutations." (PMID 34037856, 2021). "In conclusion, we suggest that MT‐ATP6–related mtDNA disease is best defined as a mitochondrial disease spectrum disorder that includes core clinical features of cerebellar ataxia, peripheral neuropathy, and learning disability, with or without a Leigh‐like phenotype." (PMID 31187502, 2019). "Similarly, decreased expression of mitochondrial genes such as MT‐CO1, MT‐CYB, and MT‐ATP6 in dopaminergic subclusters points to impaired oxidative phosphorylation, which could contribute to parkinsonism, ataxia, and other movement disorders arising from energy failure in motor circuitry." (PMID 41355579, 2026).
neuropathy (27 papers, 2010 to 2025). A disorder affecting the nervous system that manifests with pain, tingling, numbness, and/or muscle weakness. "A mutation (m.8993T > G) in MT-ATP6 in mitochondrial DNA (mtDNA) causes the neuropathy, ataxia, retinitis pigmentosa (NARP) syndrome by impairing mitochondrial energy production." (PMID 40629055, 2025). "Thus, our result that neuropathy-causing MT-ATP6 mutation affects the assembly of ATP synthase is consistent with impaired dynamics as a possible disease mechanism." (PMID 34635923, 2022). "Our findings suggest that MT‐ATP6–related mitochondrial DNA disease is best conceptualized as a mitochondrial disease spectrum disorder and should be routinely included in genetic ataxia and neuropathy gene panels." (PMID 31187502, 2019).
NARP syndrome (14 papers, 2011 to 2025). A clinically heterogeneous progressive condition characterized by a combination of proximal neurogenic muscle weakness, sensory-motor neuropathy, ataxia, and pigmentary retinopathy. "The first variant in the mt-DNA affecting ATP6 of ATP synthase was described in 1990 as m.8993T>G on MT-ATP6, and found in four members of a family affected by NARP syndrome." (PMID 38396915, 2024). "For example, the same MT-ATP6 variant can cause MILS or NARP syndromes if the heteroplasmy found in stable tissues is higher than 90% or between 70 and 90%, respectively." (PMID 38396915, 2024). "Specifically, MT‐ATP6 mutations block the generation of ATP, leading to the symptoms in NARP syndrome." (PMID 39619320, 2024). "We studied seven unrelated index‐cases with MILS or NARP syndrome (five familial and two isolated) and 10 family members carrying various HL of MT‐ATP6 mutations." (PMID 33476484, 2021). "Thus, a mutation load of > 90% is frequently found in MILS syndrome and MT-ATP6 mutations in 70–90% of mitochondrial DNA often cause NARP syndrome." (PMID 34037856, 2021). "Two sibs with RP and sensorimotor peripheral neuropathy (NARP syndrome) carried the m.8993T>G (p.Leu156Arg) substitution in subunit 6 of the mitochondrial ATPase gene (MT-ATP6)." (PMID 36460718, 2022). "In particular, NARP is most frequently caused by heteroplasmic point mutations in MT-ATP6, an mtDNA gene encoding subunit 6 of mitochondrial H (+)-ATPase (complex V); 70–90% of mutation loads usually manifest as NARP syndrome; meanwhile, higher levels of mutants may lead to MILS." (PMID 35466209, 2022). "This study focused on the epilepsy phenotype of patients with MT‐ATP6‐related MILS and NARP syndrome and investigated the correlation of mutant HL with seizures, EEG, and qEEG findings." (PMID 33476484, 2021).
breast carcinoma (11 papers, 2011 to 2025). "An additional mutation in the mtATP6 gene, m.8601A>G, has been found in early stage breast cancer, suggesting that missense mutations in this gene increase the risk of developing tumors." (PMID 26462158, 2015). "Regarding both mitochondrial genes, it has been recently shown that mtATP6 has a higher mutation frequency than mtATP8, at least in breast cancer." (PMID 26462158, 2015). "The occurrence of A8860G with one or more missense variants within the MT-ATP6 gene appeared to be associated with the risk of (G8584A, T8701G, T8705C, T8843C, A8962G or G9064T) or protection from (G8572A, A8812G) breast cancer at an individual level in the present study." (PMID 36758048, 2023). "Interestingly, they observed that two mitochondrial genes, namely MT-ATP6 (complex V) and MT-CYB (complex III) showed the highest number of variants in the high-risk breast cancer patients." (PMID 27136895, 2016). "Missense variants A8860G in the MT-ATP6 gene and, C14766T and A15326G in the MT-CYB gene which had a prevalence of 93% or more among our patients and controls were seen at a 100% prevalence in a cohort of Malaysian breast cancer patients comprising of women of Chinese, Malay and Indian ethnicities." (PMID 36758048, 2023).
maternally-inherited Leigh syndrome (11 papers, 2011 to 2025). "Also, neurons derived from induced pluripotent stem cells (iPSCs) from a patient with maternally inherited Leigh syndrome (MILS), carrying a mutation in the MT‐ATP6 gene, showed reduced glutamate toxicity after rapamycin treatment." (PMID 30309855, 2018). "Phenotypic variations in disease severity depend mainly on the fraction of mutated mtDNA percent (i.e., the level of heteroplasmy), as observed in Maternally inherited Leigh syndrome (MILS) and neuropathy, ataxia and retinis pigmentosa (NARP) syndrome, caused by subunit a (MT-ATP6) mutations." (PMID 24786291, 2014).